RINL (Ras and Rab interactor like)
Description:
Guanine nucleotide exchange factor (GEF) for RAB5A and RAB22A that activates RAB5A and RAB22A by exchanging bound GDP for free GTP. Plays a role in endocytosis via its role in activating Rab family members (By similarity).
Synonyms: FLJ45909
Tractability: PROTAC: ubiquitination databases record sites on it.
Gene: Protein-coding gene on chromosome 19 (38,867,830 to 38,878,275, reverse strand). Ensembl gene ENSG00000187994.
Subcellular location: Cell projection, ruffle; Cytoplasmic vesicle
Subcellular location (Human Protein Atlas): Nucleoplasm; Vesicles
Pathways (Reactome):
Vesicle-mediated transport: RAB GEFs exchange GTP for GDP on RABs
Gene Ontology:
Molecular function: guanyl-nucleotide exchange factor activity; small GTPase binding
Biological process: endocytosis; vesicle-mediated transport
Cellular component: cytosol; endocytic vesicle; ruffle; actin cytoskeleton; cytoplasmic vesicle
Genetic constraint (gnomAD): Loss-of-function variants: 37 observed, 51.33 expected, observed/expected ratio (o/e) 0.72, 90% interval 0.55 to 0.95. The upper end of that interval is the gene's LOEUF score, 0.95, which puts it in group 4 of 6, group 1 being the genes least tolerant of losing a copy. Missense variants: 684 observed, 675.1 expected, observed/expected ratio (o/e) 1.01, 90% interval 0.95 to 1.08. Synonymous variants: 281 observed, 289.67 expected, observed/expected ratio (o/e) 0.97, 90% interval 0.88 to 1.07.
Homologues: Orthologues: chimpanzee RINL (99% identical), macaque RINL (88% identical), dog RINL (74% identical), pig RINL (73% identical), guinea pig RINL (70% identical), mouse Rinl (68% identical), rat Rinl (66% identical), Drosophila melanogaster spri (20% identical), Caenorhabditis elegans rin-1 (17% identical), Drosophila melanogaster Rabex-5 (10% identical), Caenorhabditis elegans rabx-5 (9% identical). Paralogues in human: RIN3 (26% identical), RIN2 (26% identical), RIN1 (23% identical), GAPVD1 (16% identical), VPS9D1 (13% identical), RABGEF1 (12% identical).